POSTN (periostin)
Diseases named in the same sentence as POSTN in open-access papers (continued):
Sharing a sentence is not in itself a finding about the gene and the disease.
osteoporosis (continued). "We have, therefore, evaluated the role of Periostin in osteoporosis in the cell culture model." (PMID 39940700, 2025). "This article reviews the research results and potential applications of periostin in osteoporosis." (PMID 38487345, 2024). "The serum level of periostin could be a potential biochemical parameter for osteoporosis in Chinese postmenopausal women." (PMID 35327993, 2022). "In a previous study, Periostin has been shown to participate in osteoblast differentiation through Wnt/β-Catenin signaling, which suggests that Periostin may be a novel target for osteoporosis therapy." (PMID 34591063, 2021). "Moreover, POSTN is not only a regulator of bone formation and bone mineral density but also a potential biomarker for osteoporosis and fracture." (PMID 34513869, 2021). "In the present study, we found that Periostin was reduced in BMSCs derived from the osteoporosis rat model and that overexpression of periostin could enhance the osteogenic ability of BMSCs, in part by activating the ILK/Akt/GSK3β axis." (PMID 34591063, 2021). "POSTN may be a new target gene for anti-osteoporosis treatment, and, due to its wide expression profile, its role in the regulation of stem cell function is emerging." (PMID 34513869, 2021). "Besides, POSTN knockout mice (POSTN–/–) have exhibited osteoporosis with decreased bone mineral density (BMD), deteriorated bone microarchitecture and low bone strength." (PMID 33409280, 2020). "Based on our findings, Periostin may play a crucial role in the pathogenesis of osteoporosis." (PMID 39940700, 2025). "Our findings suggest that Periostin may serve as a therapeutic target of osteoporosis." (PMID 34591063, 2021). "POSTN could, therefore, be a novel target gene for anti-osteoporosis therapies." (PMID 32420385, 2020). "The implications of this are that Periostin is essential for osteoblast differentiation and ECM buildup, but at a different time in bone regeneration, and in osteoporosis, it acts as a regulator of bone mass by suppressing OPG secretion." (PMID 39940700, 2025). "However, it is not possible to conclude from our finding alone whether Periostin mRNA decreases with age as a cause or consequence of osteoporosis." (PMID 39940700, 2025). "The 17β-E2/periostin/Wnt/β-catenin pathway can enhance the osteogenesis of bone marrow stromal cells (BMSCs) in ovariectomized (OVX) rats, thereby decreasing osteoporosis." (PMID 36611844, 2022). "In line with the expression level of Periostin, ILK, pAkt and pGSK3β levels were also reduced in BMSCs derived from female rats with osteoporosis." (PMID 34591063, 2021). "Collectively, our study indicated the role of POSTN in the osteogenesis and stemness of OVX-BMSCs and proves that 17β-E2 reduces osteoporosis and promotes osteogenesis through the POSTN-Wnt/β-catenin pathway." (PMID 32420385, 2020). "This indicates that alternative splicing of Periostin has no special function in the pathogenesis of osteoporosis." (PMID 39940700, 2025). "The Periostin mRNA expression in osteoblasts from osteoporosis patients was observed to be, non-significantly, two-thirds lower than that of patients with normal bone density." (PMID 39940700, 2025). "Periostin isoforms are tissue-specific and can serve different functions, for example by enhanced integrin binding, but their impact on osteoporosis is not yet known." (PMID 39940700, 2025). "At the same time, Periostin inhibits OPG secretion and may, therefore, contribute to bone resorption in osteoporosis." (PMID 39940700, 2025). "Although its role in bone-regulating cells and the formation of an extracellular meshwork is relatively known, there is little evidence for the effects of Periostin in the pathogenesis of osteoporosis." (PMID 39940700, 2025). "It is questionable whether this correlation exists in osteoporosis, when Periostin may no longer be involved in ECM formation and collagen cross-linking." (PMID 39940700, 2025).
osteoporosis (continued). "POSTN is also capable of activating canonical Wnt/β-catenin signaling in BMSCs and chondrocytes, resulting in induced MMP13 and ADAMTS4 expression to accelerate the pathogenesis of OA, and mediates estrogen-induced osteogenic differentiation of BMSCs in ovariectomized rats to reduce osteoporosis." (PMID 34513869, 2021).
pulmonary hypertension (11 papers, 2012 to 2024). Increased pressure within the pulmonary circulation due to lung or heart disorder. "More recently, periostin levels were associated with the severity of viral bronchiolitis, as children with severe pulmonary hypertension had high levels of this protein as compared to children with mild pulmonary hypertension (8,887 ± 1,582 pg/ml vs. 5,016 ± 1,017 pg/ml)." (PMID 31214165, 2019). "We demonstrated that periostin was involved in the development of different types of experimental pulmonary hypertension (PH)." (PMID 35318760, 2022). "It is noteworthy that elevated expression of periostin in the arterial wall was found in a hypoxia-induced model of pulmonary hypertension." (PMID 34063373, 2021). "In a study involving hypoxia-induced pulmonary hypertension (HPH), miR205, miR-20a-5p, and miR-541 were predicted to target POSTN, and these microRNAs might compete with several lncRNAs and circRNAs for binding to POSTN." (PMID 38370408, 2024).
airway hyperresponsiveness (10 papers, 2012 to 2024). "One report shows that allergen-induced increases in serum IgE and airways hyperresponsiveness are exaggerated in periostin-deficient mice challenged with inhaled Aspergillus fumigatus antigen." (PMID 30473714, 2018). "Furthermore that serum levels of periostin are associated with airway hyperresponsiveness (AHR) to methacholine and mannitol, we also hypothesized that periostin may be correlated with AHR induced by exercise in asthmatic children." (PMID 30937129, 2019). "Another report using periostin-deficient mice and anti-periostin neutralizing antibody shows that periostin is required for IgE synthesis and airways hyperresponsiveness in mice challenged with inhaled aeroallergen, house dust mite." (PMID 30473714, 2018). "Periostin is necessary for house-dust mite-induced airway hyperresponsiveness in mice through dendritic cell activation." (PMID 27830727, 2016). "Moreover, periostin is known to facilitate the activation of dendritic cells, thereby rendering airway hyperresponsiveness and airway inflammation in mice." (PMID 28659663, 2017).
atherosclerosis (10 papers, 2014 to 2025). A disease characterized by the build-up of fatty material and calcium deposition in the arterial wall resulting in partial or complete occlusion of the arterial lumen. "Inflammation is a fundamental pathogenic factor in the development of atherosclerosis, and both periostin and TNF-α are important proinflammatory cytokines involved in the inflammatory response that can regulate each other to promote an inflammatory response." (PMID 36127647, 2022). "The underlying mechanism may be that lncRNA-H19 inhibits periostin expression at least partially by sponging let-7, and periostin acts as a regulator of inflammatory diseases including atherosclerosis." (PMID 32698876, 2020). "Periostin, originally cloned from a mouse osteoblast cell line, is a highly conserved extracellular matrix protein and is implicated in the pathophysiology of tumor development, arthritis, atherosclerosis, and inflammatory diseases." (PMID 27313402, 2016). "Dysregulation of periostin expression arises in fibrosis, wound healing tissues, inflammatory diseases such as arthritis, atherosclerosis, infarcted myocardium, tumorigenesis, and metastasis." (PMID 36224629, 2022). "Periostin has functions in cancer, fibrosis, and inflammatory diseases such as infarcted myocardium, arthritis, atherosclerosis, and asthma." (PMID 36224629, 2022). "Increasing evidence supports the involvement of periostin in the pathophysiological processes of stroke and atherosclerosis." (PMID 30082879, 2018). "Recently, we were able to show that genetic single Stabilin deficiency and anti-Stabilin antibody therapy in different atherosclerosis-prone mouse models ameliorate atherosclerosis, likely through altered immune cell activation mediated by a plasma proteome switch including TGFBi and POSTN." (PMID 37446152, 2023). "Periostin is an extracellular matrix protein known to regulate VSMC migration and osteoblastic switch, and has been suggested to promote atherosclerosis and vascular calcification." (PMID 41068431, 2025). "Periostin (OSF-1) has been reported to be a critical player in the inflammatory microenvironment in various disorders such as airway inflammation, skin inflammation, atherosclerosis, and fibrosis." (PMID 39940657, 2025).
rheumatoid arthritis (10 papers, 2015 to 2025). A chronic, systemic autoimmune disorder characterized by inflammation in the synovial membranes and articular surfaces. "Periostin was investigated as a biomarker for rheumatoid arthritis-associated interstitial lung disease (RA-ILD)." (PMID 38002712, 2023). "POSTN+ fibroblasts in rheumatoid arthritis synovium, which were reported to be high in POSTN and collagen genes, have been linked to the ‘fibroid’ pathotype of rheumatoid arthritis." (PMID 40232153, 2025). "It has been identified in rheumatoid arthritis (RA) and osteoarthritis (OA) joints with a recent study identifying periostin as a key regulator in RA synoviocyte migration/invasion associated with pannus formation." (PMID 30202513, 2018). "If periostin improves rather than aggravates the inflammation in psoriasis, this might also turn out to be true in other inflammatory diseases as well, such as rheumatoid arthritis, where periostin was elevated in patients with disease remission compared with healthy controls." (PMID 39201477, 2024). "In vitro assays have confirmed that expression of POSTN and TWIST1 are elevated in fibroblast-like synoviocytes (FLSs) of rheumatoid arthritis patients (RA-FLSs) and are crucial for the migration and invasion of FLSs stimulated with interleukin (IL)-1β." (PMID 25981515, 2015). "Periostin is also upregulated in chronic inflammations such as IBD and rheumatoid arthritis (RA)." (PMID 34512647, 2021). "Periostin expression was also assessed in rheumatoid arthritis (RA) and non-inflammatory osteoarthritis (OA) synovium and synovial fluid immunohistochemistry and ELISA respectively." (PMID 30202513, 2018).
allergic asthma (9 papers, 2020 to 2025). A asthma with a basis in a pathological type I hypersensitivity reaction. "It has long been linked to allergic asthma as serum periostin is often used as a biomarker for disease severity." (PMID 37035669, 2023). "Periostin is an often overlooked, yet important mediator in fibrosis and, in particular, allergic asthma." (PMID 35387027, 2021). "Cultured pericytes were treated with the pro-fibrotic mediators TGF-β and periostin in order to simulate the conditions of fibrosis seen in allergic asthma." (PMID 35387027, 2021). "This study has demonstrated that the production of periostin is initiated by IL-13, a Type 2 cytokine with well-known roles in allergic asthma." (PMID 35387027, 2021). "Nevertheless, periostin levels were significantly different (P = 0.001) according to endotypes, with mean values of 45.7 (27.9) ng/mL in allergic asthma, 64.7 (24.9) ng/mL in AERD, 59.0 (27.6) ng/mL in late-onset eosinophilic asthma, and 28.3 (13.3) ng/mL in non-eosinophilic asthma." (PMID 37744693, 2023). "Periostin levels correlated to endotypes (P = 0.001): 45.7 (27.9) ng/mL in allergic asthma (n = 16 patients), 64.7 (24.9) in aspirin-exacerbated respiratory disease (n = 14), 59.0 (27.6) ng/mL in late-onset eosinophilic asthma (n = 4), and 28.3 (13.3) ng/mL in non-eosinophilic asthma (n = 18)." (PMID 37744693, 2023). "It is hypothesized that periostin may be produced by profibrotic pericytes and contribute to the remodeling observed in allergic asthma." (PMID 35387027, 2021). "Periostin has been shown to contribute to several aspects of tissue remodeling in allergic asthma." (PMID 35387027, 2021). "This indicates that there was a large concentration of periostin present in the inflamed lung, which may contribute to the remodeling observed in allergic asthma." (PMID 35387027, 2021). "Top “Th2-high” genes with marker potential in allergic asthma are POSTN and SERPINB2." (PMID 32157178, 2020). "However, serum periostin has been investigated as a biomarker for eosinophilic inflammation and airway remodeling in allergic asthma, supporting the notion that elevated periostin levels in multiple body compartments is a feature of allergic airway inflammation and remodeling." (PMID 35387027, 2021). "Markers such as periostin and PAI-2 also traditionally serve as markers of “type 2–high” molecular endotype of allergic asthma." (PMID 40408478, 2025). "As these periostin expressing cells were not present in the lung sections from healthy, PBS exposed mice, periostin evidently contributes to the tissue remodeling seen around the large airways in allergic asthma." (PMID 35387027, 2021).
type 2 diabetes (9 papers, 2015 to 2024). "Previous studies have discovered periostin was significantly up‐regulate in type 2 diabetes before the onset of significant albuminuria, which was closely associated with DKD progression." (PMID 39570100, 2024). "Specifically, periostin levels are increased both in the renal tissue and in the urine of patients with type 2 diabetes, as well its levels are positively correlated with ageing, high albuminuria and the decline of renal function." (PMID 35883655, 2022). "In healthy subjects with normal glucose tolerance, expression of human periostin is significantly higher in sWAT compared to vWAT, and this difference was blunted in patients with impaired glucose tolerance or overt type 2 diabetes." (PMID 30088333, 2018). "The following novel findings emerged: urinary periostin was increased in normoalbuminuric type 2 diabetes compared with healthy controls." (PMID 25884625, 2015). "In conclusion, the results of the study identify periostin as a novel renal biomarker associated with albuminuria and GFR levels in type 2 diabetes patients." (PMID 25884625, 2015). "Several kidney tissues from type 2 diabetic patients and controls were randomly collected for periostin immunostaining." (PMID 25884625, 2015). "Regression analyses found a strong association between increasing urine levels of periostin correlated with declining GFR and increasing albuminuria independently of the degree of blood pressure, glycemic and lipid levels in patients with type 2 diabetes." (PMID 25884625, 2015). "The study has also demonstrated that urinary periostin levels increased before the onset of microalbuminuria and that urinary periostin can be an early biomarker of renal tubular injury in normoalbuminuric patients with type 2 diabetes compared with controls." (PMID 25884625, 2015). "Univariate and multivariate linear regression analyses between urine periostin levels and other parameters in patients with type 2 diabetes." (PMID 25884625, 2015). "The AUC to diagnose established normoalbuminuric, microalbuminuric and macroalbuminuric type 2 diabetes using urine periostin were 0.78 (95%CI, 0.71 to 0.86), 0.99 (95%CI, 0.98 to 1.00) and 0.95 (95%CI, 0.91 to 0.98), respectively." (PMID 25884625, 2015). "The study indicates that increased urine periostin levels can be detected in patients with type 2 diabetes before the onset of significant albuminuria." (PMID 25884625, 2015). "In the present study, we investigated whether periostin is a mediator of renal disease in type 2 diabetes." (PMID 35883655, 2022). "By contrast with our results, in two Chinese studies involving young women with polycystic ovary syndrome and adult obese patients with type 2 diabetes, periostin concentration was directly correlated with BMI and triglycerides and inversely correlated with HDL-cholesterol." (PMID 34063373, 2021). "This suggests that periostin may be a biomarker for early kidney damage in type 2 diabetic nephropathy, and measuring urine periostin in patients with type 2 diabetes may help to provide an early diagnosis and advanced interventions." (PMID 33241962, 2020). "Aging process with averaged GFR at 70 mL/min/1.73 m2 in normoalbuminuric type 2 diabetes might explain the higher levels of urine periostin." (PMID 25884625, 2015). "Urine periostin ELISA also demonstrated high performance for the diagnosis of established normoalbuminuric, microalbuminuric and macroalbuminuric type 2 diabetes (AUC 0.78 (95%CI, 0.71 to 0.86), 0.99 (95%CI, 0.98 to 1.00) and 0.95 (95%CI, 0.91 to 0.98), respectively)." (PMID 25884625, 2015). "The present study describes the rising urine excretion of periostin in type 2 diabetes patients." (PMID 25884625, 2015). "Measuring periostin in the urine may provide an earlier diagnosis and advanced interventions in type 2 diabetes patients." (PMID 25884625, 2015).
type 2 diabetes (continued). "Finally, although urinary periostin increased in normoalbuminuric type 2 diabetes compared with healthy controls, mean age and estimated GFR differed between both groups." (PMID 25884625, 2015). "The appearance of urine periostin in type 2 diabetes patients but not in healthy controls underscores its value as a potential biomarker for kidney injury in albuminuric and nonalbuminuric type 2 diabetes." (PMID 25884625, 2015). "The clinical implications of urinary periostin activities in patients with type 2 diabetes have not been evaluated." (PMID 25884625, 2015). "The author found that urinary periostin levels increase before the onset of albuminuria and that urinary periostin may act as an early biomarker of renal cell injury in type 2 diabetic patients without albuminuria." (PMID 36551967, 2022).
acute kidney injury (8 papers, 2017 to 2024). Sudden and sustained deterioration of the kidney function characterized by decreased glomerular filtration rate, increased serum creatinine or oliguria. "Related studies have found that urinary periostin which was closely associated with the progression of IgA nephropathy could predict renal failure." (PMID 39570100, 2024). "One of the markers mentioned in previous studies on renal function in patients with renal failure for various reasons is periostin (POSTN)." (PMID 37130146, 2023). "The present study identified the impact of periostin for acute kidney injury induced by rhabdomyolysis." (PMID 36359784, 2022). "First, the expression of periostin was measured by real-time PCR with samples obtained at day 0, 3, 21, and 42 after 50% glycerol injection in the rhabdomyolysis-induced acute kidney injury model." (PMID 36359784, 2022). "Targeting POSTN might propose a new therapeutic strategy against the development of acute renal failure." (PMID 36359784, 2022). "We made periostin-null mice to examine the role of POSTN in acute renal failure." (PMID 36359784, 2022). "However, the effect of periostin in a rhabdomyolysis-induced acute kidney injury model was unknown." (PMID 36359784, 2022). "In animal and cell models of CKD or acute kidney injury-to-CKD transition, periostin and disease severity were significantly related, and renal injury was alleviated upon inhibition of periostin." (PMID 34607314, 2021).